CCL5 (C-C motif chemokine ligand 5)
Diseases named in the same sentence as CCL5 in open-access papers (continued):
Sharing a sentence is not in itself a finding about the gene and the disease.
atherosclerosis (continued). "Unlike CC-chemokine inhibitor 35K, the M3 protein is capable of sequestering members from all chemokine classes, specifically key chemokines involved in atherosclerosis progression including CCL2, CCL5 and CX3CL1, while displaying selectivity in its binding to individual members." (PMID 28282403, 2017). "Assessment of circulating chemokines found that there were no significant changes in either CCL2 or CCL5 in the plasma for either model of atherosclerosis progression with M3." (PMID 28282403, 2017). "CCL5/RANTES, and its receptor CCR5 are known to contribute to neuronal function as well as to metabolic disorders such as type 2 diabetes mellitus, obesity, atherosclerosis and metabolic changes after HIV infection." (PMID 27898058, 2016). "These genes included the chemokines CCL5, CXCL10, CCL8, CXCL9, CCRL2, which were also up-regulated in carotid or coronary human plaques, as shown here, and together reflect pro-atherogenic responses in human atherosclerosis." (PMID 25196434, 2014). "However, evidence now supports a role for CCR5 and its ligands CCL3 (MIP-1a), CCL4 (MIP-1b), and CCL5 (RANTES) in the initiation and progression of atherosclerosis." (PMID 22577254, 2012). "The purpose of our study was to evaluate whether PPB attenuates CCL5/CCR5 expression induced by HFD and attenuates VSMC proliferation and reduced phenotype switching, which is a pathophysiological characteristic of atherosclerosis or intimal hyperplasia induced by HFD." (PMID 32727125, 2020). "Furthermore, deficiency of CCR5 (the receptor for CCL5, a chemokine also known as RANTES) in ApoE-/- mice does not appear to be protective in the early stages of atherosclerosis." (PMID 21526997, 2011).
asthma (124 papers, 2004 to 2025). "For CCL5, Saad-El-Din demonstrated that serum CCL5 levels are greater in subjects with severe or moderate asthma as compared to subjects with mild asthma and are associated with blood eosinophil number." (PMID 28848734, 2017). "Therefore, CCL5 is associated with a wide range of immune-mediated diseases, including asthma, airway inflammatory disorders, pathogen infection, rheumatoid arthritis, and atopic dermatitis." (PMID 39598462, 2024). "CCL5 was identified as having a relationship with Th2 cells in the pathogenesis of respiratory allergic diseases, particularly regarding its association with inflammation in asthma." (PMID 35743888, 2022). "Plasma levels of CCL5 and IL-5 or eosinophil counts in the peripheral blood may not be useful diagnostic biomarkers to evaluate airway inflammation and monitor asthma severity." (PMID 32467785, 2020). "Thus IL‐13 and CCL5 may be associated with asthma exacerbation, although this relationship remains unclear." (PMID 33534941, 2021). "In conclusion, the plasma levels of CCL5 and IL-5, as well as the eosinophil count in peripheral blood, may not be useful diagnostic biomarkers to evaluate airway inflammation and monitor asthma severity during sandstorms, especially if the patients have used ICS." (PMID 32467785, 2020). "Among them, hsa-miR-1248, hsa-miR-23b-5p, STAT3, Quercetin, Tretinoin, Particulate Matter, Simvastatin, Asthma, Hepatitis B, Hepatitis C, Diabetes Mellitus, and Pulmonary Fibrosis have an interaction relationship centred on CCL5." (PMID 40461634, 2025). "It is associated with disease severity in conditions such as atopic dermatitis and asthma and regulates CCL5-induced mast cell migration via CCR4 in vivo." (PMID 40278124, 2025). "Both CCL2 and CCL5 promote the accumulation of macrophages and granulocytes in the airways of asthma patients, thereby increasing the severity of airway inflammation." (PMID 39432538, 2024). "A recent publication indicates that CCL5 is a potential bridge between type 1 and type 2 inflammation in asthma." (PMID 39598462, 2024). "Since we are interested to understand the regulation of T2 inflammation in asthma, we studied if F2RL1 rs1529505 is associated with TH2 cells, TH2 cells’ ligand PGD2, cytokines IL-13 and CCL5, a T cell chemoattractant." (PMID 38308375, 2024). "Chemokines such as CXCL8 (IL-8), CCL2 (MCP-1), and CCL5 (RANTES) are significantly upregulated during asthma-related lung inflammation." (PMID 39902079, 2024). "Ruxolitinib also inhibits the release of CCL5, a chemokine involved in asthma exacerbations, from bronchial epithelial cells in vitro." (PMID 39188724, 2024). "CCL5 is involved in immune s surveillance, inflammatory response, tumour formation and metastasis, and in the pathogenesis of inflammatory diseases in asthma and cancer." (PMID 37759440, 2023). "The airway epithelium expresses CCL2, CCL3, CCL4, CCL5, CCL11, and CXCL5, which are associated with asthma." (PMID 35743888, 2022). "For the inflammatory cytokines in the lung, the contents of TNF-α, TNFR2, CXCL-9, CCL-12, CCL-9, CCL-2, and CCL-5 in the asthma model group were higher than those in the control group, while the contents of GM-CSF and IL-1α were decreased." (PMID 35600943, 2022). "In a study of childhood asthma, CCL5 and CCL7 were significantly increased in the bronchial alveolar lavage (BAL) fluid of children with asthma and was associated with higher BAL eosinophils." (PMID 36177009, 2022). "We made the observation that GC insensitivity present in ASM cells derived from severe asthma was also reported to be gene-specific with CCL5, IL-6 and CCL11 being resistant to dexamethasone (or fluticasone), while CXCL10 still being repressed by either GCs." (PMID 35387008, 2021). "It has been reported that chemokine (C‐C motif) ligand 5 (CCL5) is involved in the exacerbation of asthma by RNA virus infections." (PMID 33534941, 2021).
asthma (continued). "High levels of CCL2 and CCL5 in the BALF along with increased IL-5 in patients with asthma induce eosinophil infiltration and activation." (PMID 33806085, 2021). "It was already reported that this key cell of the allergic response during asthma, the eosinophil, is activated by cytokines (IL-5) and chemokines (CCL5, CCL11) via the activation of MSK1." (PMID 33450992, 2021). "For instance, a dietary intervention with 1% GOS suppressed the increased BALF leukocyte numbers and CCL5 and IL-13 levels in a murine house dust mite-induced asthma model." (PMID 34684515, 2021). "The chemokines CCL3, CCL4, and CCL5 are all associated with the migration of macrophages and other leukocytes through their binding to CCR1, CCR4, and CCR5, and have been linked with asthma." (PMID 31024538, 2019). "CD16+ monocytes preferentially express receptors for chemokines such as CCL3 and CCL5; these chemokines are increased in patients with asthma, indicating a potential link between CD16+ monocytes and asthma pathophysiology." (PMID 26658828, 2015). "The present inhibition of CCL5 and the association between increase in airway CCL5 and deterioration of asthma at stopping steroid treatment support the view that this protein may have a central role in maintaining inflammatory processes in rhinitis and asthma." (PMID 20459697, 2010). "In animal models of asthma the overexpression of IL-9 causes BAL eosinophilia, peribronchial accumulation of collagen and increased BAL levels of CCL5 and CTGF." (PMID 18315837, 2008). "In patients with asthma, monocytes are recruited into the airways by the actions of CCL5, which was increased in our study at the mRNA level; however, no notable change was observed at the released protein level, suggesting distinct modulation of its mRNA expression and protein release." (PMID 39432538, 2024). "In the study on treatment of asthma, it can diminish the expression of IL-4, IL-5, IL-13, IL-17A, IgE, CCL5, and CCL11, inhibit NF-kB- and JNK-mediated inflammatory signaling, and reduce oxidative damage through decreasing the activity of ROS and increasing SOD." (PMID 36588723, 2022). "In addition, the contents of TNF-α, TNFR2, CXCL-9, CCL-12, CCL-9, CCL-2, and CCL-5 in the asthma model group were higher than those in the control group, while the contents of GM-CSF and IL-1α were decreased." (PMID 35600943, 2022). "Next, to determine whether experimental asthma attenuates the increase in Ccl4 and Ccl5 expression observed in the optic nerves of Nf1OPG mice at 12 and 24 weeks of age, quantitative real-time PCR was performed." (PMID 34880260, 2021). "Therefore, the JAK1–PI3K pathway is a key regulator for synergistic CCL5 production, which is a potential therapeutic target for severe asthma." (PMID 33534941, 2021). "Increased levels of CCL5 have been reported in patients with asthma." (PMID 32467785, 2020). "To further clarify whether the WTD can adjust the apoptosis state of EOS to achieve the purpose of alleviating asthma, we use ELISA method to detect IL-5, IL-10, CSF, CCL5, TGF-β, and IFN-γ in rat serum." (PMID 29713367, 2018). "Interestingly, genes previously associated with asthma, such as CCL5 (RANTES), CXCL10 (IP10), LGALS9, CX3CL1, C5AR1, and CDHR3 fall into these three different groups." (PMID 25706956, 2015). "In an animal model of asthma AOP-RANTES/CCL5 decreases allergen-induced airway inflammation suggesting that targeting CCR5 may also be effective." (PMID 18315837, 2008). "In contrast, in both asthma and COPD, naturally occurring and RV-induced experimental exacerbations are associated with an increase in tissue neutrophils as well as eosinophils, also of interleukin-8 (IL-8,CXCL8) and CC-type chemokine ligand 5 (CCL5) gene expression." (PMID 39598462, 2024).
asthma (continued). "Although a number of proinflammatory mediators may contribute to asthma per se, and may even be derived from fibroblasts, in pilot studies using a multiplex assay, we found IL-6, IL-8, CCL5 and TSLP to be particularly expressed, and importantly changed by TNFα treatment." (PMID 36760534, 2023). "Additionally, CCL5 (RANTES) has been identified in the airways of patients with asthma." (PMID 33806085, 2021). "In addition, the analysis of CCL5 and IL-5 in the sputum was outside the scope of this work, and thus, consequent studies should investigate the probability that sputum cytokine expression is a good indicator of asthma activity." (PMID 32467785, 2020). "However, targeting the chemokine CCL5 with antibodies in a murine model of allergic airway disease resulted in the inhibition of airway inflammation, suggesting the importance of CCL5 in determining the severity of asthma." (PMID 32467785, 2020). "Finally, our in vitro findings indicated that CCL5 may play a role in monocyte recruitment in rhinovirus-induced asthma exacerbation." (PMID 31969885, 2019). "Moreover, Chemokine (C-C Motif) Ligand 5 (CCL5) was significantly reduced within the central airways in severe asthma, as was the epithelial gene expression for the MHC class II, DO alpha (HLA-DOA), which regulates peptide loading and is involved in antigen presentation." (PMID 28045928, 2017). "As reported, IL-4, IL-5, and IL-13 are proinflammatory cytokines; eotaxin is a pivotal chemokine crucial for eosinophil homing to the lungs of asthma patients; and CCL4, CCL5, MCP-1, and GM-CSF recruit macrophages." (PMID 40050290, 2025). "In Asthma 3, JUN is also repressed while the expression patterns of IL7R, IL32, and CCL5 are more similar to healthy controls." (PMID 41550933, 2025). "Specific chemokines, such as CCL11, CCL5, and CXCL12, have been shown to play critical roles in airway inflammation in asthma by promoting the migration and activation of eosinophils and DCs, thereby driving excessive inflammatory responses in the airways." (PMID 41036310, 2025). "CCR3 is one of the most relevant chemokine receptors in asthma, and its ligands are CCL3, CCL5, CCL11, and CCL13." (PMID 35743888, 2022). "Comparing the asthma model group to the dexamethasone group, the levels of G-CSF, CCL-9, CCL-5, and TNFR2 in the former group were higher." (PMID 35600943, 2022). "Severe asthma was differentiated from moderate disease by CXCLI, growth related oncogene (GRO), regulated on activation, normal T expressed and secreted (RANTES, CCL5), IL-12, interferon (IFN)-γ and IL-10." (PMID 35722499, 2022). "The levels of CCL2, CCL3, and CCL5 in the BALF and CCL11 in plasma were significantly higher in asthma patients than in control subjects." (PMID 35743888, 2022). "It was also established, that the biomarker CCL5, in the nasal epithelium during RSV bronchiolitis, is strongly predictive of physician-diagnosed asthma." (PMID 34734387, 2021). "RANTES (CCL5) is a chemotactic and activating factor for eosinophils, and a candidate mediator in asthma." (PMID 34068739, 2021). "Cultures from asthma donors had higher CXCL10 and CCL5 gene expression (along with a further 44 genes) after RV infection, compared to healthy donors." (PMID 32499788, 2020). "In summary, epithelial-derived mediators such as CCL5, IL-1, IL-8, IL-6 and TNF-α drive mesenchymal-mediated inflammation that promotes TH2, eosinophilic and neutrophilic inflammation in different asthma subtypes." (PMID 32679790, 2020). "The results demonstrated the significant elevation of total Ig E, CCL5, and CCL11 level in asthma group compared with control group (p < 0.05)." (PMID 33013383, 2020). "Sputum CCL5 and CXCL11 levels were substantially higher in subjects with asthma than in subjects with COPD, with area under the ROC curves (ROC AUCs) of 0.74 (95% CI, 0.67-0.82; P < .0001) and 0.72 (95% CI, 0.64-0.80; P < .0001), respectively." (PMID 25129678, 2015).
asthma (continued). "In genomic studies of asthma several genes have been found to be significantly induced, of which some significant biomarkers are Chemokine ligands (CCL8, CCL5, CCL11, and CCL24), SERPINs (SERPINB2, SERPINB4, and SERPINA1) and CarboxypeptidaseA3." (PMID 24409194, 2014). "Although other chemokines, such as CCL3L1 and CCL5, have already been examined in detail to assess their role in asthma, little is known about the possible influence of CCL15 on asthma." (PMID 23258953, 2012). "Among genes identified in asthma GWAS, ROBO1, RORA, HLA-DQB1, IL2RB and PDE10A showed most consistent expression patterns and from asthma candidate genes, e.g. NOD1, EDN1, CCL5 and HLA-G were identified." (PMID 21699702, 2011). "The CCL5 -471C>T SNP, which we found might be associated with MS in HLA-DRB1*1501 negative patients, is of potential functional relevance, as it creates a new transcription factor binding site, and has shown associations with atopic dermatitis, atopy and asthma." (PMID 16872505, 2006). "A previous study showed that MAP3K19, a component of the MAPK pathway, suppressed allergic airway inflammation in asthma models by modulating epithelial response to stimuli such as TWEAK and TGFβ1, thereby reducing the production of pro-inflammatory cytokines such as RANTES (CCL5)." (PMID 40598285, 2025). "CXCL-10, CCL-5,and TNF-R2 were the strongest discriminatorsof an asthma attack." (PMID 38339210, 2024). "It was also found in the DNA methylation expression patterns of peripheral monocytes of eight obese children with asthma and that the decrease in promoter methylation of CCL5 was related to the occurrence of non-specific inflammation." (PMID 36303550, 2022). "Moreover, this TCM attenuation of Ccl5 was observed in both CD4+ and CD8+ T cell populations following experimental asthma induction in Nf1OPG mice." (PMID 34880260, 2021). "The findings reveal that experimental asthma induction impairs microglia Ccl5 support of optic glioma formation and growth without altering T-cell Ccl4 expression." (PMID 34880260, 2021). "Indeed, we confirmed the elevated expression of CCL5 and CCL11 in BALF samples from OVA-induced asthma model." (PMID 33013383, 2020). "Many of the mediators (e.g., TGF-β1/2, ET-1, TSP-1, CCL5, IL-1, IL-8, IL-6, TNF-α, BNP), highlighted in this review to drive epithelial-mesenchymal cross-talk have previously been identified in asthma pathogenesis." (PMID 32679790, 2020). "It is known that CCL5, CCL11, and CCL24 may contribute to the airway recruitment of fibrocytes in severe asthma." (PMID 31548841, 2019). "CCL5 mRNA expression in our data is increased in children with asthma after HRVI (although this was not statistically significant, p = 0.08), whereas an unremarkable increase was observed in children without asthma." (PMID 30485264, 2018). "Additionally, CCL5 (aka RANTES), CXCL10 (aka IP-10) were also chosen for comparison experiments because these chemokines were known mediators in asthma that are differentially sensitive to vitamin D." (PMID 26207385, 2015). "While there was no general over-representation of asthma genes among differentially expressed genes, some asthma genes were consistently differentially expressed in multiple developing lung transcriptomes, e.g. NOD1, EDN1, CCL5, RORA and HLA-G suggesting key functional roles in lung development." (PMID 21699702, 2011). "However, differential expression of some asthma genes was consistent in both developing human and murine lung, e.g. NOD1, EDN1, CCL5, RORA and HLA-G." (PMID 21699702, 2011). "In addition, there was no significant increase in CCL5 levels in the plasma of patients with asthma (mean 641 pg/ml) relative to that in the healthy controls (588 pg/ml)." (PMID 32467785, 2020). "Taken together, these results suggest that CCL5 may not be a useful marker of asthma severity during sandstorms, especially if the patients used ICS treatments during the storms." (PMID 32467785, 2020).